MDM2 (MDM2 proto-oncogene)
Description:
Also acts as a ubiquitin ligase E3 toward itself and ARRB1. Promotes proteasome-dependent ubiquitin-independent degradation of retinoblastoma RB1 protein. Inhibits DAXX-mediated apoptosis by inducing its ubiquitination and degradation. Also a component of the TRIM28/KAP1-ERBB4-MDM2 complex which links growth factor and DNA damage response pathways. Mediates ubiquitination and subsequent proteasome degradation of DYRK2 in nucleus. Ubiquitinates IGF1R and SNAI1 and promotes them to proteasomal degradation. Ubiquitinates DCX, leading to DCX degradation and reduction of the dendritic spine density of olfactory bulb granule cells (By similarity). Ubiquitinates DLG4, leading to proteasomal degradation of DLG4 which is required for AMPA receptor endocytosis (By similarity). Negatively regulates NDUFS1, leading to decreased mitochondrial respiration, marked oxidative stress, and commitment to the mitochondrial pathway of apoptosis. Binds NDUFS1 leading to its cytosolic retention rather than mitochondrial localization resulting in decreased supercomplex assembly (interactions between complex I and complex III), decreased complex I activity, ROS production, and apoptosis.
Synonyms: Hdm2; MGC5370; ACTFS; HDMX; LSKB
Tractability: Small molecule: a drug acting on it is in phase 2 or 3 trials; a structure with a bound ligand is known; a high-quality ligand is known; it has a high-quality binding pocket; it belongs to a druggable protein family. Antibody: its Gene Ontology location is reachable by antibodies, with high confidence. PROTAC: it is named in the literature on targeted protein degradation; UniProt records ubiquitination sites on it; ubiquitination databases record sites on it; a small molecule that binds it is known.
Target class: Other nuclear protein
Chemical probes: AM-6761 (high quality), AM-8735, IDASANUTLIN (high quality), MD-224 (high quality), MI-888 (high quality), NVP-CGM097, Navtemadlin (high quality), PD006213, PD007327, PD052871, PD080702, PD080967, PD081033, PD081440, PD081603, PD081807, PD082323, PD082614, PD082925, PD083468, and 20 more
Gene: Protein-coding gene on chromosome 12 (68,808,175 to 68,845,544, forward strand). Ensembl gene ENSG00000135679.
Subcellular location: Nucleus, nucleoplasm; Cytoplasm; Nucleus, nucleolus; Nucleus
Subcellular location (Human Protein Atlas): Cytosol; Nucleoplasm; Centriolar satellite; End piece; Mid piece; Principal piece
Pathways (Reactome):
Gene expression (Transcription): NPAS4 regulates expression of target genes; Regulation of RUNX3 expression and activity
Metabolism of proteins: SUMOylation of transcription factors; SUMOylation of ubiquitinylation proteins; Ub-specific processing proteases
Cellular responses to stimuli: Oncogene Induced Senescence; Oxidative Stress Induced Senescence
Disease: Constitutive Signaling by AKT1 E17K in Cancer; Signaling by ALK fusions and activated point mutants
Cell-Cell communication: Degradation of CDH1
Neuronal System: Trafficking of AMPA receptors
Signal Transduction: AKT phosphorylates targets in the cytosol
Gene Ontology:
Molecular function: 5S rRNA binding; disordered domain specific binding; enzyme binding; identical protein binding; ligase activity; NEDD8 ligase activity; protein binding; protein domain specific binding; ribonucleoprotein complex binding; SUMO transferase activity; ubiquitin binding; ubiquitin protein ligase activity; ubiquitin protein ligase binding; ubiquitin-protein transferase activity; zinc ion binding; peroxisome proliferator activated receptor binding; receptor serine/threonine kinase binding
Biological process: amyloid fibril formation; apoptotic process; cellular response to gamma radiation; cellular response to hypoxia; establishment of protein localization; negative regulation of DNA-templated transcription; negative regulation of transcription by RNA polymerase II; positive regulation of mitotic cell cycle; positive regulation of proteasomal ubiquitin-dependent protein catabolic process; proteasome-mediated ubiquitin-dependent protein catabolic process; protein autoubiquitination; protein catabolic process; protein destabilization; protein localization to nucleus; protein ubiquitination; protein-containing complex assembly; regulation of cell cycle; regulation of protein catabolic process; response to antibiotic; ubiquitin-dependent protein catabolic process; negative regulation of apoptotic process; and 34 more
Cellular component: cytoplasm; cytosol; nuclear body; nucleolus; nucleoplasm; nucleus; protein-containing complex; transcription repressor complex; endocytic vesicle membrane; plasma membrane; glutamatergic synapse; postsynaptic density
Genetic constraint (gnomAD): Loss-of-function variants: 9 observed, 48.3 expected, observed/expected ratio (o/e) 0.19, 90% interval 0.11 to 0.32. The upper end of that interval is the gene's LOEUF score, 0.32, which puts it in group 1 of 6, group 1 being the genes least tolerant of losing a copy. Missense variants: 339 observed, 496.77 expected, observed/expected ratio (o/e) 0.68, 90% interval 0.62 to 0.75. Synonymous variants: 155 observed, 168.81 expected, observed/expected ratio (o/e) 0.92, 90% interval 0.81 to 1.05.
Homologues: Orthologues: macaque MDM2 (99% identical), chimpanzee MDM2 (94% identical), pig MDM2 (92% identical), dog MDM2 (89% identical), guinea pig MDM2 (89% identical), rat Mdm2 (82% identical), mouse Mdm2 (80% identical), tropical clawed frog mdm2 (56% identical), zebrafish mdm2 (45% identical). Paralogues in human: MDM4 (32% identical).
Diseases named in the same sentence as MDM2 in open-access papers:
MDM2 is named in the same sentence as 540 diseases in open-access papers, as found by Europe PMC text mining. Sharing a sentence is not in itself a finding about the gene and the disease. The quoted sentences say what the papers report.
breast carcinoma (372 papers, 1995 to 2026). "Elevated MDM2 expression is associated with poor prognosis across various cancers, including dedifferentiated liposarcoma, breast cancer, and glioblastoma." (PMID 41515979, 2025). "Currently, the MDM2 inhibitor milademetan is being combined with fulvestrant to treat ER+/HER2-advanced breast cancer patients with GTAG3 mutations in tumors and/or ctDNA." (PMID 40949156, 2025). "The distribution of PTEN-inactivating mutations and MDM2/4 amplification were similar between primary and R/M breast cancer among three subtypes." (PMID 40182039, 2025). "For instance, in sarcomas and glioblastomas, MDM2 amplification correlates with poor prognosis, while in breast cancer, elevated MDM2 levels are associated with reduced disease-free survival, particularly in estrogen receptor-positive tumors." (PMID 41170373, 2025). "Studies have shown that in 5.9% of breast cancer patients, the MDM2 gene was amplified approximately 17-fold in tumor cells, and there were post-translational modified MDM2 splice variants." (PMID 38741108, 2024). "In patients with breast cancer who have alternatively spliced MDM2 transcripts, these variants tend to be more biologically aggressive, with greater axillary lymph-node involvement and greater necrosis." (PMID 38741108, 2024). "Our results confirmed that MDM2 downregulation is linked to upregulation of p21 and p27 expression in breast cancer cells." (PMID 36672146, 2023). "Upregulation of p21 associated with MDM2 downregulation has been linked to apoptosis induction in either prostate and breast cancer cells." (PMID 36672146, 2023). "A recent study presented GATA3 and MDM2 were synthetically lethal in ER+ breast cancer, where MDM2 was a novel therapeutic target in GATA3‐deficient subsets." (PMID 34146382, 2022). "Our results provide evidence that MDM2 is a selected vulnerability in breast cancer with GATA3-mutation and/or loss of GATA3." (PMID 35440675, 2022). "The presence of this SNP reduces the risk of both ovarian and breast cancers, highlighting the relevance of MDM2 fine-tuning for cancer development." (PMID 34307167, 2021). "In breast cancer, although the incidence of amplification or mutation of MDM2 is relatively low, increased abundance of MDM2 protein occurs in ~ 38% of all breast cancers and is more frequent among ER-positive than in ER-negative tumours." (PMID 32787886, 2020). "MDM2 is also associated with tumor metastasis and formation of the transfer site (such as in prostate, colon and breast cancers and osteosarcomas)." (PMID 32359357, 2020).
breast carcinoma (continued). "A study confirmed that MDM2 overexpression is associated with trastuzumab resistance in human epidermal growth factor receptor-2 (HER-2) positive breast cancer." (PMID 31440117, 2019). "High levels of MDMX and low levels of MDM2 have been shown to correlate with acquisition of the mesenchymal phenotype associated with metastasis of breast cancers." (PMID 30642351, 2019). "We found the impact of the three MDM2 splice variants on potential cellular endpoints upon chemotherapy treatment of breast cancer cell lines to be limited." (PMID 28415963, 2017). "We found that overexpression of MDM2 caused the occurrence of EMT and knockdown of MDM2 led to mesenchymal-epithelial transition (MET) in breast cancer cells in vitro and in vivo." (PMID 27184007, 2016). "MDM2 splicing variants are tumorigenic in mouse models and have been associated with tumor progression in breast carcinomas." (PMID 27129163, 2016). "InuA decreased cell proliferation and induced G2/M phase arrest and apoptosis in breast cancer cells; it also led to a decrease in MDM2, NFAT1 and proteins associated with cell proliferation, and an increase in apoptotic signal related proteins." (PMID 27105525, 2016). "In our previous study, we demonstrated that MDM2 promotes invasion and metastasis of breast cancer by upregulating MMP9 expression, causing increased extracellular matrix breakdown." (PMID 27184007, 2016). "MDM2 overexpression is associated with a more aggressive phenotype and decreased overall survival, and contributes to migration and invasion in breast cancer." (PMID 27184007, 2016). "The MDM2 oncogene is genetically amplified and/or overexpressed in breast cancer patients and is positively associated with poor prognosis and high incidence of metastasis." (PMID 27105525, 2016). "Here, we show that the EMT phenotype in multiple cellular models and in clinical prostate and breast cancer samples is associated with a decrease in MDM2 and increase in MDMX expression." (PMID 26416355, 2015). "First, MDM2 is overexpressed in human breast cancer and associated with breast cancer progression, metastasis and drug resistance." (PMID 25739118, 2015). "This is consistent with other observations where MDM2 overexpression is linked to breast tumors and hyperplastic alveolar nodules in mice and also human breast cancers." (PMID 25664318, 2015). "Other specific gene amplifications, for instance in breast cancer such as ERBB2 or MDM2 are associated with high grade cancer and have strong prognostic significance." (PMID 25013904, 2014). "In the present study, we investigated the impact of 40-bp ins/del polymorphism of MDM2 on risk of breast cancer in a sample of Iranian population." (PMID 25326024, 2014). "In the present study, we aimed to evaluate the impact of 40-bp insertion/deletion (ins/del) polymorphism on the promoter of MDM2 and susceptibility to breast cancer in a sample of Iranian population." (PMID 25326024, 2014).
breast carcinoma (continued). "Of these, two SNP pairs (APEX1-rs1130409 *RPAP1-rs2297381 and MLH1-rs1799977 *MDM2-rs769412) showed the strongest statistical association with breast cancer (P<7.3×10−3), with modest FDR values of 0.30 and 0.49, respectively." (PMID 23755158, 2014). "In summary, we have provided the evidence that the 40-bp ins/del polymorphism in the promoter of MDM2 gene increases the risk of breast cancer in a sample of Iranian population." (PMID 25326024, 2014). "A recent study demonstrated that both single nucleotide polymorphism (SNP) 285 and SNP 309 in MDM2 (murine double mutant 2) are found in breast cancer and can affect the binding of Sp1 to the MDM2 promoter." (PMID 23148884, 2012). "It has been suggested that the single nucleotide polymorphism 309 (SNP309, T -> G) in the promoter region of the MDM2 gene is important for tumor development; however, with regards to breast cancer, inconsistent associations have been reported worldwide." (PMID 19144119, 2009). "In this study, we found that MDM2 SNP309 was associated with the risk of breast cancer incidence as well as an earlier onset of this disease in female Taiwanese population (124 breast cancer cases)." (PMID 19144119, 2009). "The first reason for this study was that relevant information on the effect of the MDM2 SNP309 on the risk of breast cancer remains sparse for Asian populations, including Taiwanese." (PMID 19144119, 2009). "Taken together, this hospital-based case-control study suggests that MDM2 SNP309 is associated with the risk of breast cancer in Taiwanese women." (PMID 19144119, 2009). "The intron 1 region of MDM2 was examined in a Scottish population of 299 breast cancer patients and 275 cancer free controls to establish any associations between MDM2 SNPs and breast cancer." (PMID 18828900, 2008). "A recent study proposed a model in which an estrogen-signaling pathway allows the G-allele of MDM2 SNP309 to accelerate breast cancer formation." (PMID 17537232, 2007). "MDM2 gene amplification is found in a number of tumour types, including sporadic breast cancers, and overexpression of MDM2 is associated with accelerated tumour development and failure to respond to treatment." (PMID 16563154, 2006).